IL18 (interleukin 18)
Diseases named in the same sentence as IL18 in open-access papers (continued):
Sharing a sentence is not in itself a finding about the gene and the disease.
Hepatic steatosis (continued). "As showed in our study, HCLD feeding decreased hepatic expression of Il-18 in the livers, which was in accordance with the previous study that IL-18 negatively related to hepatic steatosis and inflammation." (PMID 26608583, 2015). "A role for IL-18 has been postulated in the development of hepatic steatosis since both serum IL-18 concentration and hepatic Il18 mRNA expression are elevated in lipopolysaccharide-treated leptin deficient ob/ob mice and high fat diet fed-C57BL/6 mice." (PMID 25251155, 2014). "While prior work has also implicated inflammasome activation in the development or hepatic steatosis, our findings do not suggest systemic measures of IL-6, IL-18, TNF-α are associated with greater hepatic fat deposition." (PMID 40700400, 2025). "Furthermore, elevating IL-18 levels by disrupting macrophage phosphatase SHP2 protects mice from HFD-induced hepatic steatosis." (PMID 40243151, 2025). "IL-18 is induced upon NLRP1 activation and decreased upon NLRP1 loss, and its production could prevent hepatic steatosis." (PMID 40243151, 2025). "AIM2 inflammasome released IL-18 and IL-1 β after activation, which promoted hepatic steatosis." (PMID 39600708, 2024). "This suggests that ezetimibe treatment may contribute to improvement in hepatic steatosis and the inflammatory process by reducing IL-18." (PMID 35307033, 2022). "In the serum of fatty liver patients, the GT concentration was significantly increased, suggesting that the enzyme is hypersynthesized in the liver and participates in liver damage together with IL‐18." (PMID 33720453, 2021). "IFN‐γ produced by IL‐18 has the effect of strongly inducing the development of fatty liver in rats." (PMID 33720453, 2021). "Furthermore, IL‐18 serum concentration was higher in patients with liver cancer, hepatitis C, hepatitis B, and fatty liver disease compared to healthy controls." (PMID 33720453, 2021). "Since the serum IL‐18 concentration in patients with fatty liver disease was high, correlations between IL‐18 serum concentration in these patients and high‐density lipoprotein (HDL), low‐density lipoprotein (LDL), triglycerides (TRIG), and total cholesterol (TC) were analyzed." (PMID 33720453, 2021). "Therefore, IL-18 can be considered to play a functional role in predicting advanced liver steatosis and fatty liver in obese patients." (PMID 31485221, 2019). "IL-18 level was also significantly higher in obese children with advanced liver steatosis." (PMID 29854715, 2018). "Interestingly, exogenous administration of IL-18 with IL-12 to BALB/c mice induces fatty liver in an IFN-γ dependent manner, suggesting that both cytokines play an important role in the inflammatory cascade leading to NAFLD." (PMID 25251155, 2014). "Consistently, excessive lipid accumulation could further promote TLR4/NF‐κB signaling to trigger the leakage of proinflammatory cytokines (TNF‐α, IL‐6, IL‐1β, and IL‐18), thus exacerbating the vicious cycle of inflammatory responses in the liver to aggravate fatty liver progression." (PMID 40501499, 2025). "In the logistic regression analysis IL-18 (OR-1.006, 95% CI for OR—1.001–1.010, and p = 0.018) and triglycerides (OR-1.015, 95% CI for OR—1.003–1.028, and p = 0.012) were the only measures useful in the differentiation of obese patients with liver steatosis confirmed using 1HMRS." (PMID 29854715, 2018). "Significant correlations between IL-18 and alanine aminotransferase (ALT), gamma glutamyltransferase (GGT), TG, high-sensitivity C-reactive protein (hsCRP), and the degree of liver steatosis have been reported." (PMID 34966296, 2021). "Mitsuyoshi reported that hepatic IL-18 mRNA and serum IL-18 levels were significantly higher in NAFLD patients than those in controls, which correlated significantly with hepatic steatosis." (PMID 31485221, 2019). "Significant correlations between IL-18 and ALT, GGT, triglycerides, hsCRP, and the degree of liver steatosis were demonstrated." (PMID 29854715, 2018).
Hepatic steatosis (continued). "Accordingly, in the present study we have shown that both increased levels of Il12a, Il12b, Il18, Ifng, Tnfa, and Il10 mRNA expression seen in the liver of HFH fed mice and hepatic steatosis were reduced in HFL fed mice." (PMID 25251155, 2014). "Cytokines, particularly interleukin (IL)-6, IL-18, and tumor necrosis factor (TNF)-α, could promote intra-hepatic lipid peroxidation and peripheral lipolysis, contributing to hepatic steatosis." (PMID 40700400, 2025). "IL-18 knockout mice (IL-18−/−) fed an American lifestyle-induced obesity syndrome (ALiOS) diet, which induces hepatic steatosis but not NASH, were protected from early liver injury." (PMID 40794228, 2025). "We evaluated IL-6, IL-18, and TNF-a because these might promote intra-hepatic lipid peroxidation and peripheral lipolysis, which could contribute to development of hepatic steatosis." (PMID 40700400, 2025). "The IL‐18 coating antibody and the Eu3+‐labeled detection antibody were used for the IL‐18‐TRFIA to detect serum IL‐18 concentration in patients with liver cancer, hepatitis B, hepatitis C, autoimmune hepatitis, fatty liver disease, and healthy controls." (PMID 33720453, 2021). "Measurement of serum IL-18 showed ability to differentiate children with fatty liver from those without steatosis." (PMID 29854715, 2018). "Obtained results demonstrated that hepatopathic children with liver steatosis measured with 1HMRS have significantly higher levels of serum IL-18 as well as steatosis score of 2 or 3 in USG than those without liver steatosis in 1HMRS." (PMID 29854715, 2018). "The concentration of IL-18 was significantly higher in obese children with advanced liver steatosis compared to children without steatosis (p = 0.027)." (PMID 29854715, 2018). "Significant positive correlations of IL-18 with ALT (r = 0.2, p = 0.036), AST (r = 0.21, p = 0.032), GGT (r = 0.23, p = 0.016), TG (r = 0.21, p = 0.027), hsCRP (r = 0.36, p = 0.014), and the degree of liver steatosis (USG) (r = 0.2, p = 0.044) were found." (PMID 29854715, 2018). "However, in contrast to IL-18 increase of ferritin serum level was not related to liver steatosis, which is contrary to data from adult population that showed predictive role of high serum ferritin as a risk factor for steatosis." (PMID 29854715, 2018). "Our results showed that the expression of AIM2 is positively correlated with IL-1β and IL-18 expression in CHB patients and not correlated in the control fatty liver disease patient group." (PMID 26290184, 2015).
HIV-1 infection (25 papers, 2012 to 2025). The type species of lentivirus and the etiologic agent of acquired immunodeficiency syndrome (AIDS). "We identified a cluster of IRPs (cluster 7), including CXCL11, CXCL9, TNF, CXCL10, and IL18, which was closely associated with T cell dysregulation during chronic HIV-1 infection." (PMID 36408648, 2023). "The plasma levels of TGF-β1 and IL-18 in primary HIV-1 infection were both positively associated with T cell activation level at set-point (6 months after acute infection) and together able to predict 74% of the T cell activation variation at set-point." (PMID 23056251, 2012). "There is currently limited clinical data on the role of IL-18 during HIV-1 infection in resource-limited settings." (PMID 37937297, 2023). "We also found a high systemic burst of several plasma cytokines (IFN-γ, TNF-α, IP-10, and IL-18) in agreement with the charateristic cytokine storm of acute HIV-1 infection in humans." (PMID 36800238, 2023). "As a putative mechanism, we demonstrated that NK cells increased surface ADAM17 expression via elevated plasma IL-18 levels during HIV-1 infection, which in turn reduced surface CD16 downregulation." (PMID 37669308, 2023). "Nevertheless, this cohort study provides evidence for the dynamic changes and clinical significance of plasma IL-18 after long-term ART in the process of HIV-1 infection." (PMID 37384047, 2023). "We report here significant increases of circulating protein levels of IL-18 at day 10 and 24 post-HIV-1 infection indicating a full blown inflammasome activity in humanized mice." (PMID 36800238, 2023). "Our findings indicate that HIV-1 infection is associated with a reduced capacity of CD161+ CD4+ T cells to produce cytokines following stimulation with IL-12 and IL-18." (PMID 33322496, 2020). "It is important to note that the MAIT cell responsiveness to IL-12 and IL-18 stimulation is preserved in matched donor samples before and after HIV-1 infection." (PMID 31937782, 2020). "The inflammasome activation ends with the active forms of IL-1β and IL-18 that are increased during HIV-1 infection, promoting disease progression." (PMID 29963050, 2018). "It was demonstrated that IL-18 inhibited the production of HIV-1 p24 antigen in vitro whereas during the chronic stage of HIV-1 infection, IL-18 directly stimulated viral replication." (PMID 27821119, 2016). "Our study highlights the role of TGF-β1 and two IFN-inducible cytokines (IP10 and IL-18) in determining the immunological set-points during HIV-1 infection." (PMID 23056251, 2012). "As expected, HIV-1 infection in the vehicle group induced a potent cytokine storm with elevated plasma levels of the inflammasome-related cytokines IL-18 but also IFN-γ, IP-10 and TNFα when compared to day 10 before infection (p<0.05; 0.01; 0.05; 0.001; 0.01; 0.001, respectively)." (PMID 36800238, 2023). "In conclusion, early on-treatment plasma IL-18 levels could act as a promising indicator for long-term virological response in patients with HIV-1 infection, which could be used for optimizing ART in real-world clinical practices." (PMID 37384047, 2023). "Early on-treatment plasma IL-18 could act as a promising indicator for long-term virological response in patients with HIV-1 infection." (PMID 37384047, 2023). "In these specific contexts, elevated concentrations of IL-12 and IL-18 might promote upregulation of Tim-3 on CD56bright NK cells in vivo as observed in our cohorts of subjects with early or progressive untreated HIV-1 infection." (PMID 23866914, 2013). "However, other studies argue that during the early stages of HIV-1 infection, characterized by cytokine storm, IL–18 might suppress HIV-1 by increasing the T lymphocytes’ type 1 (Th1) immune response and reducing CXCR4 co-receptor expression." (PMID 37937297, 2023).
HIV-1 infection (continued). "Thus, in the case of persistent HIV-1 infection, dysregulated plasma levels of IL-12 and IL-18 may contribute to MAIT cell activation, and activation-induced pyroptosis of MAIT cells may lead to the loss of MAIT cells in TPs." (PMID 35619176, 2022). "The STORM data demonstrated that NAIP–gp41 complexes colocalize with NLRC4 providing further evidence that upon HIV-1 infection, gp41 forms clusters with NAIP and NLRC4 where it triggers inflammasome activation leading to IL-18 secretion." (PMID 33861800, 2021). "The increased expression of IL-1β, IL-18 and caspase-1 observed herein among brains from HIV-1 infected persons was highly indicative of inflammasome activation during HIV-1 infection, prompting further investigation of this possibility." (PMID 24886384, 2014). "Indeed, IL-12 signaling has been previously linked to the regulation of cell polarization through the regulation of SAMHD1 in HIV-1 infection, showing also a direct correlation between SAMHD1 expression and IL-12/IL-18 presence." (PMID 37667113, 2024). "To show evidences of early inflammasome sensing of HIV-1 in huNSG mice upon HIV-1 infection, we quantified mRNA expression of genes involved in inflammasome activation (NLRP3, NLRP1, NLRC4, AIM2, IFI16, ASC, CASP1, IL1Β, and IL18) in hCD45+ cells from multiple tissues collected at necropsy." (PMID 36800238, 2023). "In addition, it has been shown that HIV-1 infection engages the NLRP3 inflammasome complex, however the mechanisms that regulate IL-1β and/or IL-18 have remained mostly unexplored." (PMID 33861800, 2021). "TEA and benzamil were successful in inhibiting IL-1β secretion but did not inhibit IL-18 upon HIV-1 infection." (PMID 33861800, 2021). "Many studies have previously reported a correlation between the observed increase in the production of pro-inflammatory cytokines IL-1β, IL-6, IL-18 and TNF-α; and IFN inducible chemokines CXCL9, CXCL10 and CXCL11 during the course of HIV-1 infection and the up regulation of HIV-1 replication." (PMID 29373606, 2018). "IL-12 and IL-18 are necessary for MAIT cell activation and secretion of restriction factors in vitro, and activation induced cell death may explain declining numbers of MAIT cells during HIV-1 infection." (PMID 34951583, 2021). "Importantly, this pattern was retained post-infection, with no sign of decline in IL-12 and IL-18 responsiveness during early chronic HIV-1 infection." (PMID 31937782, 2020). "Concordantly, we observed a rapid elevation in the plasma levels of several pro-inflammatory cytokines such as IFN-γ, IL-18, and IP-10 but not of IL-6 and TNFα that remained below the LOD in most of mice plasma upon HIV-1 infection." (PMID 36800238, 2023). "IL-18 and TGF-β1 have never been studied before for their predictive value at the early stage of HIV-1 infection." (PMID 23056251, 2012).
tuberculosis (25 papers, 2010 to 2025). A chronic, recurrent infection caused by the bacterium Mycobacterium tuberculosis. "In humans, the IL-18 promoter gene −137 G/C polymorphism is a risk factor for tuberculosis in the Chinese population, and PBMCs of the −137 GG type had lower IL-18 production compared with the GC and CC types." (PMID 30717382, 2019). "Genetic polymorphisms in the IL-18 gene have been found to be associated with its expression in cancer, tuberculosis, HBV infection, and various other diseases." (PMID 25405235, 2014). "Inflammasome-derived cytokines, IL-1β and IL-18, and complement cascade have been independently implicated in the pathogenesis of tuberculosis (TB)-immune reconstitution inflammatory syndrome (TB-IRIS), a complication affecting HIV+ individuals starting antiretroviral therapy (ART)." (PMID 33788899, 2021). "Further studies on rBCG/IL-18 as a new prototype vaccine strain are needed to evaluate practical implications in the fight against tuberculosis." (PMID 35455364, 2022). "IL-12 plays an important role in anti-tuberculosis cell-mediated immunity, and in addition to IL-18 are regarded as the primary inducers of IFNy production in inflammatory reactions." (PMID 31481950, 2019). "IL-1β is upregulated in the lungs of tuberculosis patients, and both IL-1β and IL-18 are secreted from M. tuberculosis and M. marinum infected macrophages in vitro." (PMID 20463815, 2010). "In addition, it was confirmed that metformin increased proinflammatory cytokines (TNF-α, IL-1α, IL-1β, IL-6, IL-18, IL-8, and IFN-α) in Mycobacterium tuberculosis (causative agent of tuberculosis)-infected macrophages." (PMID 37700364, 2023). "Other researchers have shown that M. tuberculosis-stimulated culture supernatants from people diagnosed with TB have lower concentrations of IL-18 compared to those from healthy TST converters." (PMID 37261336, 2023). "There is a growing evidence supporting important roles for IL-18 and IFN γ in tuberculosis (TB) infection and anti-tuberculosis immunity." (PMID 33412574, 2021). "The study was aimed to assess IL-18, IL-18 binding protein (IL-18BP), IL-18R, IFN-γ, and IL-37 mRNA expression in patients with active tuberculosis (ATB) and healthy volunteers with latent M.tb-infection (LTB) or M.tb-uninfected healthy controls (Control)." (PMID 32521630, 2020). "IL-18 is produced by the innate immune system, acts as a precursor to IFN-γ production and is highly increased in patients with advanced tuberculosis." (PMID 21966464, 2011). "Previously, we described elevated levels of cytokines/chemokines such as IL-18, IFN-γ, CXCL-10, CXCL-9, G-CSF, IL-6, CXCL-1, VEGF, and PDGF-BB in plasma samples of tuberculosis (TB) patients with active pulmonary disease." (PMID 37685858, 2023). "For example, the plasma levels of IL-18, CCL-2, and CXCL10 differed depending on whether patients developed TB IRIS without a previous episode (unmasking IRIS) or developed it as an unexpected worsening of tuberculosis (paradoxical IRIS)." (PMID 23688318, 2013). "In ATB, but not LTB individuals, the overexpression of IL-18 and IL-18BP, as well as a significant increase in IFN-γ mRNA expression, might be considered as a manifestation of active tuberculosis disease." (PMID 32521630, 2020).
acute coronary syndrome (24 papers, 2013 to 2025). Signs and symptoms related to acute ischemia of the myocardium secondary to coronary artery disease. "Following interleukin-1β inhibition in patients with prior acute coronary syndrome, a residual inflammatory risk was associated with persistently high IL-18 levels after treatment." (PMID 39334884, 2024). "We aimed to assess associations between circulating IL‐18 concentrations and cardiovascular outcomes in patients with acute coronary syndromes (ACS)." (PMID 31596518, 2019). "Similarly, IL-18 was shown to be more commonly associated with peripheral arterial occlusive disease, and cerebrovascular events, whereby an elevated level of IL-18 was shown to be evident in the plasma of acute coronary syndrome patients." (PMID 35000611, 2022). "Previous research on acute coronary syndrome concluded that the IL-18/IL-10 ratio had a positive predictive value for disease effects and adverse hospital outcomes." (PMID 39080003, 2024). "Our findings indicate significantly higher interleukin (IL)‐18 levels in acute coronary syndrome (ACS) patients versus the control group, while IL‐1β levels remained consistent." (PMID 38402570, 2024). "For example, in the setting of acute coronary syndrome, colchicine was effective in suppressing interleukin IL-1b, IL-18 and IL-6, which was attributed to inflammasome inhibition." (PMID 36128202, 2022). "Elevated plasma IL‐37, IL‐18, and IL‐18BP levels are also observed in patients with inflammatory conditions, such as acute coronary syndrome, where NLRP3 is involved." (PMID 35429346, 2022). "This study investigated the potential modifying effects of the level of the serum interleukin-18 (IL-18) on the association between BDNF methylation status and long-term cardiovascular outcomes in patients with acute coronary syndrome (ACS)." (PMID 36499595, 2022). "Moreover, colchicine administration contributed to the reduction in IL-1β, IL-18, and IL-6 in patients with acute coronary syndrome." (PMID 34440608, 2021). "Nicorandil suppresses the inflammatory cytokines IL-1β, IL-1, IL-6, IL-10, IL-18, IL-19 and TNF-α in acute coronary syndrome patients." (PMID 34595611, 2023). "Acute coronary syndrome patients with CCs in culprit lesions had a higher expression of NLRP3, IL-1β, and IL-18, and had more vulnerable plaque characteristics than patients without CCs." (PMID 36386333, 2022). "In patients with the acute coronary syndrome,NLRP3, IL-18 precursor, IL-18 andIL-1β levels were higher in subjects with acute myocardialinfarction and angina pectoris and correlated with serum total cholesterol, LDL,and OX-LDL levels, relative to normal subjects." (PMID 39076616, 2022). "In studies of acute coronary syndrome (ACS), colchicine has been shown to prevent NLPR3 inflammasome-induced caspase-1 activation, leading to decreased levels of interleukin IL-1b, IL-18, and IL-6 and CRP and a reduction in mortality from major cardiovascular events." (PMID 33133323, 2020).